CCNP (cyclin P)
Description:
Seems to be involved in the regulation of proliferation and migration.
Synonyms: CNTD2; FLJ13265
Tractability: No criterion of Open Targets' tractability assessment is met for any kind of drug.
Gene: Protein-coding gene on chromosome 19 (40,222,208 to 40,226,697, reverse strand). Ensembl gene ENSG00000105219.
Subcellular location: Nucleus
Gene Ontology:
Molecular function: cyclin-dependent protein serine/threonine kinase regulator activity
Cellular component: nucleus; cyclin-dependent protein kinase holoenzyme complex
Genetic constraint (gnomAD): Loss-of-function variants: 18 observed, 19.09 expected, observed/expected ratio (o/e) 0.94, 90% interval 0.65 to 1.4. The upper end of that interval is the gene's LOEUF score, 1.4, which puts it in group 5 of 6, group 1 being the genes least tolerant of losing a copy. Missense variants: 420 observed, 396.19 expected, observed/expected ratio (o/e) 1.06, 90% interval 0.98 to 1.15. Synonymous variants: 225 observed, 186.23 expected, observed/expected ratio (o/e) 1.21, 90% interval 1.08 to 1.35.
Homologues: Orthologues: chimpanzee CCNP (98% identical), macaque CCNP (91% identical), dog CCNP (54% identical), pig CCNP (54% identical), tropical clawed frog ccnp (36% identical), zebrafish ccnp (34% identical), Drosophila melanogaster CycB (22% identical), Caenorhabditis elegans cyb-1 (21% identical), Drosophila melanogaster CycE (21% identical), Caenorhabditis elegans cyb-2.2 (19% identical), Caenorhabditis elegans cye-1 (18% identical), Caenorhabditis elegans cyb-2.1 (17% identical), and 2 more. Paralogues in human: CCNA1 (22% identical), CCNA2 (22% identical), CCNF (22% identical), CCNO (22% identical), CCNB1 (21% identical), CCNB2 (21% identical), CCNB3 (21% identical), CCNE1 (19% identical), CCND1 (17% identical), CCNE2 (16% identical), CCNJL (16% identical), CCND2 (16% identical), and 6 more.
Diseases named in the same sentence as CCNP in open-access papers:
CCNP is named in the same sentence as 8 diseases in open-access papers, as found by Europe PMC text mining. Sharing a sentence is not in itself a finding about the gene and the disease. The quoted sentences say what the papers report.
breast carcinoma (1 paper, 2021). "Considering the high prevalence and the prognostic significance of CCNP in these cancer types, we decided to proceed with our studies in cellular models of lung, colon and breast cancer." (PMID 34604945, 2021). "The mRNA levels of CCNP were found to be higher in tumor tissues than in normal ones, especially in colon, lung and breast cancers." (PMID 34604945, 2021). "Moreover, we found that high CCNP levels correlate with a decreased overall survival in breast cancer patients (p = 0.002)." (PMID 34604945, 2021).
colon cancer (1 paper, 2021). "We found that CCNP was remarkably upregulated in spheroids compared to the corresponding adherent cells in some of the cellular models, especially in A549 lung cancer cells and HT-29 and LoVo colon cancer cells." (PMID 34604945, 2021).
colorectal cancer (1 paper, 2021). A primary or metastatic malignant neoplasm that affects the colon or rectum. "It has previously been shown that CCNP upregulation is associated with lung cancer metastasis and regional lymph node involvement in colorectal cancer patients." (PMID 34604945, 2021). "We found that CCNP increases spheroid formation in breast, lung and colorectal cancers, and upregulates the expression of stemness (CD44, CD133) and pluripotency (SOX2, OCT4, NANOG) markers." (PMID 34604945, 2021). "Remarkably, the atypical cyclin P (CCNP), also known as CNTD2, has been found to promote EMT in colorectal cancer and to endow cells with anchorage-independent growth." (PMID 34604945, 2021).
lung carcinoma (1 paper, 2021). "Noteworthy, we previously showed that high levels of CCNP are correlated with a worse clinical prognosis in lung cancer." (PMID 34604945, 2021). "Moreover, high levels of salivary CCNP mRNA have been found to markedly correlate with a worse prognosis in lung cancer patients." (PMID 34604945, 2021).
cancer (3 papers, 2020 to 2024). A tumor composed of atypical neoplastic, often pleomorphic cells that invade other tissues. "Until now, however, a mechanistic explanation for the association between high CCNP expression levels and more aggressive cancer phenotypes has been missing." (PMID 34604945, 2021). "Given the known correlation between EMT and CSC plasticity, we hypothesized that CCNP may be implicated in cancer stemness." (PMID 34604945, 2021). "Given that other cyclins have been implicated in pluripotency regulation, we hypothesized that CCNP may also play a role in cancer stemness." (PMID 34604945, 2021). "Here we present CCNP as a novel WNT pathway activator that is specifically expressed in cancer cells, providing new opportunities for the design of therapeutic strategies." (PMID 34604945, 2021). "Our results reveal CCNP as a novel player in stemness and as a potential therapeutic target in cancer." (PMID 34604945, 2021). "Here, we report that CCNP promotes sphere formation, expression of stemness and pluripotency markers and drug resistance in cancer cells." (PMID 34604945, 2021). "The effects of CCNP on cancer cell stemness and the expression of pluripotency markers and ATP-binding cassette (ABC) transporters were evaluated using Western blotting and RT-qPCR assays." (PMID 34604945, 2021). "Since markers such as CD44 and CD133 have been used to facilitate normal and cancer stem cell identification, we next examined their protein expression in adherent cell lines following CCNP upregulation using lentiviral vectors." (PMID 34604945, 2021). "Together, these results indicate that the increased expression of CCNP as observed in cancer patients may contribute to stemness-like phenotypes." (PMID 34604945, 2021). "To assess whether these observations can be reproduced in other cellular models, we extracted data from 1304 cancer cell lines (Depmap portal; Expression Public 20Q2) and confirmed that CCNP and ABC transporters are co-expressed." (PMID 34604945, 2021). "CCNP is an atypical cyclin that is clearly involved in cancer development." (PMID 34604945, 2021). "Whereas CCNP overexpression was observed in highly prevalent cancers, it was poorly expressed in normal tissues, except brain tissue, suggesting that it may represent an ideal target for the design of novel therapies." (PMID 34604945, 2021). "Considering that the self-renewal capacity of disseminated cancer cells is key to metastasis development, the unique features of CCNP may bring significant advances to the management of particularly aggressive cancers." (PMID 34604945, 2021). "CCNP upregulation increased the expression of several the drug efflux transporters tested (ABCC1 p-values: A549 = 0.0181; LoVo = 0.9358; MCF7 = 0.0247), supporting the notion that CCNP may contribute to the drug resistance of cancer cells." (PMID 34604945, 2021). "Here, we show that CCNP regulates cancer stemness through activation of the WNT pathway." (PMID 34604945, 2021). "Likewise, some proteins of the WNT pathway, which are known to function as cancer suppressors, were found to be overexpressed after CCNP knockdown." (PMID 34604945, 2021). "Given that CCNP is overexpressed in several cancers and poorly expressed in tissues, it may represent the ideal target candidate." (PMID 31420702, 2020). "To investigate whether CCNP is involved in cancer cell stemness, we cultured 6 cancer cell lines as spheroids to enrich for stemness characteristics and compared the protein expression levels of CCNP in the spheroids and parental cell lines." (PMID 34604945, 2021). "However, considering that this is the first report of a role of CCNP in cancer stemness, it is difficult to speculate whether it may occur in other cancer types as well." (PMID 34604945, 2021).
cancer (continued). "In line with our previous results, we found that CRISPR-Cas9-mediated CCNP knockout (KO) was associated with a lower expression of OCT4 in the two IPSC clones analyzed, indicating that the ability of CCNP to regulate stemness is also likely to be relevant in contexts other than cancer." (PMID 34604945, 2021). "Nevertheless, the analysis of a large panel of cell lines supports the notion that a correlation between CCNP and WNT target expression may occur in broad cancer cell contexts." (PMID 34604945, 2021). "We found that high CCNP expression correlated with a high expression of Axin2 (p < 0.0001), cyclin D1 (CCND1) (p = 0.0026), Lgr5 (p < 0.0001) and Ascl2 (p < 0.0001), suggesting that CCNP and stemness are broadly intertwined in human cancer." (PMID 34604945, 2021). "Likewise, CCNP downregulation using siRNA significantly decreased the sphere numbers (p-values: A549 = 0.0223; LoVo = 0.0067; MCF7 = 0.0242), supporting the notion that CCNP may play a critical role in cancer stemness." (PMID 34604945, 2021).
tumor (2 papers, 2021 to 2025). "We found that CCNP overexpression increased the number of cells in tumor-derived organoids (p-values: patient 1 = 0.0265; patient 2 = 0.0294), but not in normal tissue-derived organoids (p-values: patient 1 = 0.0765; patient 2 = 0.6579)." (PMID 34604945, 2021). "Next, we investigated whether CCNP upregulation increases the sphere numbers in selected cell lines of each tumor type." (PMID 34604945, 2021). "Moreover, the synergistic approach of combining chemotherapy and PDT with CCNP has been found to induce the polarization of macrophages, an increase in CD8+ T cells, and a decrease in Treg cells within the TME, suggesting the potential of CCNP in eliciting anti-tumor immune responses." (PMID 40698137, 2025).
CCNP also shares sentences with these, for which no sentence is quoted: bladder cancers (1 paper); laryngeal disease (1).